HYAL1 (hyaluronidase 1)
Diseases named in the same sentence as HYAL1 in open-access papers (continued):
Sharing a sentence is not in itself a finding about the gene and the disease.
tumor (continued). "Despite the not yet fully elucidated composition of the pericellular HA coat on tumor cells, and, in particular, the specific role of Hyal-1-synthesized LMW-HA fragments in this coat, we could demonstrate a significant impact of Hyal-1 on the development of BM in vitro as well as in vivo." (PMID 36291142, 2022). "However, it is unknown whether this correlation results from Hyal1 impact not only on HA hydrolysis 94, 95 but also on CS/DS degradation in the tumor niche." (PMID 30637950, 2019). "Furthermore, the hyaluronidase-1 (Hyal-1) is extensively distributed in the acidic tumor extracellular matrix, which degrades HA coating and the nanoparticles deliver the drug into tissues and cells.The stability studies of NAR-HA@CH-PCL-NP were carried out for three months." (PMID 29534519, 2018). "Furthermore, at present HYAL-1 is the only tumor-derived HAase that has been identified." (PMID 27419371, 2017). "Based on the current research landscape, the following directions warrant emphasis:1.Deepening Mechanistic Insights: Current studies predominantly focus on the effects of HYAL1 expression differences on ECM composition and tumor cell phenotype." (PMID 41421148, 2025). "As an extracellular matrix component, while HA was localized in the stromal compartment, HAS-2, HYAL-1, Slug, MMP-9, and N-Cadh were expressed in tumor cells." (PMID 40149256, 2025). "Hyaluronidase 1 (HYAL1), a key enzyme in hyaluronic acid (HA) metabolism, exhibits a perplexing paradoxical character in tumor biology." (PMID 41421148, 2025). "Lastly, after confirming HA reduction in all three cell lines, we assessed its impact on tumor volume, CD44 (HA’s main receptor and potential BRCA regulator), HYAL1 (which responds to HA changes), and BRCA1/2 expression." (PMID 41373491, 2025). "These compounds likely reduce low-molecular-weight HA production through coordinated regulation of HAS2 and HYAL1 expression, thereby attenuating HA-CD44 signaling pathway activity and ultimately inhibiting tumor growth." (PMID 41421148, 2025). "In univariate analysis HA, HAS-2, HYAL-1, Slug, MMP-9, and N-Cadh staining in tumor tissues significantly correlated with metastasis (p ≤ 0.002 in each case)." (PMID 40149256, 2025). "Recent studies have demonstrated that HYAL1 is highly expressed in ESCC tissues, cell lines, and tumor-derived exosomes." (PMID 41421148, 2025). "High HAS1 expression in conjunction with low HYAL1 and HYAL2 expression was observed in the tumor stage, which resulted in the accumulation of HA around tumor cells." (PMID 39858106, 2025). "HA production was also evaluated by immunohistochemistry analysis of HAS1, HAS2, HAS3, HYAL1, and HYAL2 expression on tumor cells." (PMID 39858106, 2025). "We first analyzed HA synthases HAS1, HAS2, and HAS3, hyaluronidases HYAL1 and HYAL2, ABCC5 transporter, and CD44 expression in tumor tissue (TT) in TCGA database." (PMID 39039104, 2024). "Expression of HCP5 acted as a sponge for miR-4656, preventing miR-4656 from suppressing the cell migration-inducing hyaluronidase 1 (CEMIP) gene, leading to upregulated expression of CEMIP, which plays a key role in tumour proliferation." (PMID 38052806, 2023). "Since HA undergoes dynamic regulation by HYALs, we evaluated the expression of HYAL1, HYAL2, and HYAL3 by RT-qPCR in three normal pancreatic tissue samples and seven PDAC tumor specimens." (PMID 37296612, 2023). "CDK1, ECT2, EZH2, GJB2, GPR37, GPX2, and GPX8 mRNA expression was up-regulated in the tumor group (p < 0.001), whereas GPX3, HYAL1, and TLR4 mRNA expression was down-regulated in the tumor group (p < 0.001) compared with those in the normal group." (PMID 37689745, 2023). "HYAL-1 and HYAL-2 functions are crucial in carcinogenesis; however, there is a lot of inconsistent information about their specific role in tumor growth." (PMID 36613567, 2022).
tumor (continued). "We found that Hyal-1 and, specifically, the Hyal-1-generated LMW-HA fragments, are essential for the formation of a functional pericellular HA-coat, which in turn promotes the tumor cell interaction with the brain endothelium and supports BCBM development." (PMID 36291142, 2022). "The downregulation of HYAL1 correlated with reduced CD44 and RHAMM expression, and PI3K/AKT signaling, suggesting a feedback mechanism between HA degradation and signaling in tumor cells." (PMID 31134064, 2019). "Simpson and co-workers have shown that co-expression of HYAL1 and HAS2 is the most favorable combination for tumor formation in vivo, and in vitro overexpression of HAS2 decreases the growth of tumor cells compared to controls." (PMID 29914429, 2018). "HA expression was identified diffusely in both tumor and stromal cells, whereas HAS2 and HYAL1 expressions were observed predominantly in tumor cells." (PMID 24244714, 2013). "Univariate analysis revealed significant prognostic factors, including UICC tumor stage, residual tumor, strong HA expression, strong HAS2 expression, and weak HYAL1 expression." (PMID 24244714, 2013). "We determined the mRNA expression of HYAL1, estrogen receptor (ER)-α, ERβ and progesterone receptor (PR) in EOC tumor samples and cell lines using quantitative RT-PCR." (PMID 21695196, 2011). "HYAL1 and HYAL2 have been shown to inhibit tumor growth in vivo, and it has been suggested that these two genes have major roles in the microenvironment of tumor cells." (PMID 20875124, 2010). "Despite their apparently divergent changes in different tumor types, HYAL2 and HYAL1 mRNA levels still correlated positively with each other in the whole patient material (r = 0.5; P = 0.0013)." (PMID 19435493, 2009). "The effect of expression HYAL1 and HYAL2 was studied by colony formation inhibition, growth curve and cell proliferation tests in vitro and tumour growth assay in vivo." (PMID 18725949, 2008). "As our data suggested that both HYAL1 and HYAL2 induce growth inhibition of tumours in SCID mice we tested expression of these genes in lung and renal tumours using qPCR." (PMID 18725949, 2008). "In our SCID mice experiments HYAL1 and HYAL2 genes were inactivated (or tumours didn't grow) even when the genes were repressed (water with tetracycline)." (PMID 18725949, 2008). "HYAL1 and HYAL2 expression was significantly reduced in the tumor stage." (PMID 39858106, 2025). "IHC showed that the five markers, HYAL-1, HAS-2, N-Cadh, Slug, and MMP-9 included in the CM-6 signature, were upregulated in tumor tissues from patients who developed metastasis compared to normal colon tissues and in tumors from patients who did not develop metastasis." (PMID 40149256, 2025). "In this model, overexpression of HYAL1—either alone or in combination with hyaluronan synthase isoforms HAS2 or HAS3—was found to accelerate HA turnover, thereby increasing the frequency of tumor development and metastasis." (PMID 41421148, 2025). "Integrating current evidence, we note a paradoxical phenomenon: although HYAL1 is generally overexpressed in PDAC, the characteristic hypoxic tumor microenvironment may suppress its expression." (PMID 41421148, 2025). "Notably, the Keto diet–induced tumor metastasis is dependent on BTB domain and CNC homolog 1 (BACH1) and its up-regulation of pro-metastatic targets, including cell migration–inducing hyaluronidase 1, in response to the Keto diet." (PMID 38838145, 2024). "Our analysis points out a key role of Hyal-1 and low-molecular-weight HA (LMW-HA) in the formation of a pericellular HA-coat in BC cells, which in turn promotes tumor cell adhesion, disruption, and migration through the brain endothelium in vitro as well as the extent of BM in vivo." (PMID 36291142, 2022). "Tumor progression can be inhibited by the activation of apoptosis by HYAL-1 levels exceeding 100 mU/106 cells, which are not normally produced by cancer cells." (PMID 36613567, 2022).
tumor (continued). "HYAL-1 gene expression was upregulated (log F = 6.6; p = 0.043) in the adjacent tissue, comparing dogs with tumor metastasis (n = 3) to dogs without metastasis (n = 8)." (PMID 34679042, 2021). "HYAL-1 expression was significantly increased in the adjacent tissue in the group with metastasis compared to tumor tissue in the group without metastasis." (PMID 34679042, 2021). "However, co-expression of HYAL1 and HAS2 restored the growth of tumor cells to the same level as control cells." (PMID 29914429, 2018). "As major hyaluronidases in human cells, HYAL1 and HYAL2 may control intercellular interactions and microenvironment of tumour cells providing excellent targets for cancer treatment." (PMID 18725949, 2008). "Repression of NTN4 and HYAL1 may promote cell migration and invasive growth, whereas BAI3, VWF, and EPB41L4B probably participate in angiogenesis, attachment of tumor cells to endothelial surfaces, or reflect vascular structures in the tumors." (PMID 17054779, 2006). "Not surprisingly, a number of proteins involved in tumor cell dissemination and BBB invasion were also found to associate with BCBM progression, including cathepsin-S, S100A4, RANKL, RANK, Src, HYAL1, HAS2 and prominin-1 (CD133)." (PMID 32110283, 2020). "Similarly, the Hyal family also displayed varying degree of expression with respect to tumour subtype, however HYAL1 was uniformly absent." (PMID 29510526, 2018). "However, in the present work, significant correlation between HYAL1 mRNA levels and tumor grade or stage was not obtained for any EOC subtype." (PMID 21695196, 2011). "An analysis including both normal and different tumor specimens indicated that the proportion (%) of the HAS3-positive cells of all epithelial cells correlated with hyaluronan staining in the stroma (r = 0.424, p = 0.008), and negatively with HYAL1 mRNA (r = -0.438, p = 0.005)." (PMID 19435493, 2009). "To our surprise, when we overexpressed HAS2 and HYAL1 in the luminal BC cell line MCF7, neither increased tumor cell adhesion, nor migration through the brain endothelium, nor any morphological alteration was observed." (PMID 36291142, 2022). "The results showed that HYAL1 and HYAL2 did not significantly inhibit tumour cells growth neither in vitro nor in vivo." (PMID 18725949, 2008). "Despite these differences main results are similar to our work: HYAL1 and HYAL2 do not have strong growth inhibiting activity in vitro and HYAL2 displayed some tumour suppressor activity in vivo." (PMID 18725949, 2008). "Interestingly, in our system, significantly increased expression of synthases (HAS2, HAS3) and hyaluronidases (HYAL1, HYAL3, HYAL4) was detected in the tumor cells but not in the stromal portion of TW2.6 tumors." (PMID 34869001, 2021).
cancer (41 papers, 2008 to 2025). A tumor composed of atypical neoplastic, often pleomorphic cells that invade other tissues. "In oral cancer, single-cell RNA sequencing analyses identified TGFBI and HYAL1—expressed by cancer-associated fibroblasts and endothelial cells—as robust prognostic biomarkers." (PMID 41421148, 2025). "Hyal1 has been most strongly implicated in the metastasis of several cancer types, including PCa." (PMID 23166824, 2012). "Although HYAL1 generally exhibits pro-tumorigenic properties in most cancers, its functions display significant context-dependency." (PMID 41421148, 2025). "As the only known serum-active hyaluronidase, HYAL1 represents a promising target for cancer therapy." (PMID 41421148, 2025). "A deeper understanding of this HYAL1 paradox is essential to leverage its potential for precision cancer therapies targeting HA metabolism." (PMID 41421148, 2025). "In summary, through its involvement in HA internalization, degradation, and regulation of fragment size, HYAL1 influences the progression of malignant tumors." (PMID 41421148, 2025). "3.Epigenetic Regulation: The potential influence of epigenetic modifications on HYAL1 expression and function across different cancers remains an open and promising field for exploration." (PMID 41421148, 2025). "Beyond the cancers previously discussed, HYAL1 exhibits functional diversity across various other malignancies." (PMID 41421148, 2025). "This review aims to systematically summarize recent advances in the understanding of HYAL1 in HA metabolism and in various cancer types, and to discuss future research directions and therapeutic prospects." (PMID 41421148, 2025). "The genes associated with cancer Hallmarks were GNAI2, RHOA, MAPKAPK3, HYAL1, and CISH, while the most connected were RHOA, MST1R, and ATRIP." (PMID 40028213, 2025). "In particular, overexpression of Hyal-1 and Hyal-2 during cancer metastasis has been reported in many in vitro and in vivo studies, and it has recently been suggested that HA fragments promote cancer progression through Hippo-Yap signaling." (PMID 37328876, 2023). "According to numerous studies, Hyal-1 is expressed in various cancer cells, like in the prostate, bladder, and brain, and is also connected to the human cancer cell lines MCF-7 and MDA-MB-231." (PMID 36421454, 2022). "The inhibitory role of sulfated HA (sHA) in cancer has been shown in prostate cancer cells, where it attenuates the activity of HYAL1, decreasing cancer cell proliferation and invasion." (PMID 34944559, 2021). "Further convoluting evidence explains that the role of HYAL1 in the same cancer type but different species can differ." (PMID 32258117, 2020). "In particular, the over-expression of Hyal-1 and Hyal-2 was reported during cancer metastasis in many in vitro and in vivo studies and recently it was suggested that HA fragments promote cancer progression via Hippo-Yap signaling." (PMID 32708202, 2020). "It is degraded by hyaluronidases (Hyals), with hyaluronidase-1, -2 (Hyal1, Hyal2) currently being the most studied in cancer." (PMID 28197395, 2017). "Published data on HYAL1 are somewhat contradictory with respect to its effect on the proliferation of cancer cells." (PMID 29088719, 2017). "It has been shown that Hyal-1 expression is elevated in a variety of cancer cells, for example in prostate, bladder and head tumour cells." (PMID 26343612, 2015). "Since gene expression of HYAL-1 and -2 is up-regulated under pathological conditions, hyaluronidase-mediated hyaluronan degradation appears to occur in subjects with cancer and chronic inflammation." (PMID 24212952, 2011). "There was a significant decline in HYAL1 expression from normal endometrium to the cancers (Kruskal Wallis p = 0.002)." (PMID 20875124, 2010).
cancer (continued). "A 10-fold higher expression of median HYAL1 mRNA expression was found in normal endometrium as compared to both grade 1 and grade 2 + 3 malignant tumors, and over 15-fold higher values were seen in normal post-menopausal endometrium." (PMID 20875124, 2010). "The late stages of cancer (C2 and D) seemed to prefer mostly the synergistic action of Hyal-1, PH-20 and Hyal-3." (PMID 20849597, 2010). "There was a gradual decline in HYAL1 expression from normal ovaries through benign and borderline tumors down to the cancers, with statistically significant differences between the groups (P = 0.022)." (PMID 19435493, 2009). "Instead, HYAL1 expression was consistently decreased in the cancers, with a concomitant trend to reduced hyaluronidase enzyme activity." (PMID 19435493, 2009). "The widespread presence of HYAL1 across multiple cancer types and its functional duality underscore its considerable potential in future cancer therapy—whether as a novel target for immunotherapy or as a chemosensitizing agent." (PMID 41421148, 2025). "Considering the fact that Haase, HYAL-1 in particular, could be a prognostic indicator for cancer progression, a variety of Haase inhibitors have been developed." (PMID 30135409, 2018). "Therefore, in clinic, an increased level of hyaluronidase, especially hyaluronidase-1 (HYAL1), would be a reliable marker for several types of malignant tumor." (PMID 30135409, 2018). "Although HYAL-1 expression has been shown to be decreased in a few cancer types, in several cancer systems, levels of HYAL-1 and other associated HA-family of molecules, as well as presence of low molecular mass HA fragments generated by HYAL-1, have been shown to correlate with disease progression." (PMID 27419371, 2017). "However, expression levels of HYAL1/2/3 isoforms were found to be highly variable depending of cancer types, raising the complexity of regulatory mechanisms involved." (PMID 27764788, 2016). "Therefore, the effect of HYAL1 appears to be highly context-dependent in terms of cancer type and progression." (PMID 27764788, 2016). "The inhibition of Hyal-1 using hyaluronidase inhibitors might be a new additive way in more targeted cancer treatment or in treatment of non‐cancer diseases such as arthritis and gingivitis." (PMID 26343612, 2015). "Furthermore a correlation between Hyal-1 overexpression and the malignancy of human cancer cell lines MCF-7 and MDA-MB-231 has been reported." (PMID 26343612, 2015). "The role of HYAL1 in cancer progression is unclear, but it could be hypothesized that inactivation of HYAL1 can prevent degradation of HA, leading to accumulation of HA in cancer stroma." (PMID 24244714, 2013). "HYAL2 mRNA was also reduced in cancer (p = 0.02) and correlated with HYAL1 (r = 0.8, p = 0.0001)." (PMID 20875124, 2010). "Hyal-1 and Hyal-2 were overexpressed in cancerous samples, especially in advanced stages of cancer." (PMID 20849597, 2010). "One theory to explain why decreased expression of hyaluronidase genes could lead to the development of cancer is HYAL1 and its role in apoptosis." (PMID 20875124, 2010). "Given the similarities between IPF and cancers, HYAL1 downregulation in IPF may lead to malignancy." (PMID 32258117, 2020). "Conversely, HYAL1 knockdown in ESCC cells produced opposite effects on macrophage polarization and cancer cell malignancy." (PMID 41421148, 2025). "In multivariate Cox analysis interacting with cancer recurrence, TGFBI and HYAL1 remained statistically significant for poor and good prognosis, respectively." (PMID 34869001, 2021). "Allelic imbalance is frequent in the 3p21.3 chromosome region containing HYAL1 and HYAL2 genes, suggesting that this site is important in ovarian and other cancers." (PMID 19435493, 2009). "There is a lack of fine-grained analysis of HYAL1 function tailored to specific cancer subtypes and disease stages." (PMID 41421148, 2025).